IFITM1 (interferon induced transmembrane protein 1)
Diseases named in the same sentence as IFITM1 in open-access papers (continued):
Sharing a sentence is not in itself a finding about the gene and the disease.
tumor (continued). "The IFITM1 expression pattern led us to consider the level contamination of bulk tumor H3K27ac ChIP-seq datasets with immune and stromal cell types, an unavoidable confounder when starting with primary tumor specimens." (PMID 36253360, 2022). "In the present study, we found that IFITM1 was positively correlated with most tumor-infiltrating immune cells using TIMER and ssGSEA." (PMID 36591519, 2022). "The genes COL3A1, ISLR, and IFITM1 are specific for vascular cells and show up-regulation in the tumor and down-regulation in the periphery." (PMID 35327982, 2022). "Although IFITM2 is less frequently mentioned in tumor-focused studies, this protein seems to act in a similar manner to IFITM1 and IFITM3." (PMID 36466909, 2022). "It is interesting to note that mounting evidence has shown that IFITM1 is highly expressed in many tumor tissues." (PMID 35609018, 2022). "Increased levels of the IFITM1, IFITM2, and IFITM3 proteins cause higher proliferation of tumor cells, facilitate migration and invasion and influence crosstalk between tumor and immune cells." (PMID 36466909, 2022). "Other studies have validated the importance of IFITM1 and shown correlation with poor overall and recurrence-free survival in multiple tumor types." (PMID 34680281, 2021). "For example, expression of ISGs including PLSCR1 and IFITM1/3 promotes tumor progression and invasion in clinical samples and cancer cell lines." (PMID 34680281, 2021). "In the ulcerated tumor, B cells showed increased markers associated with type-2 responses such as CCL17, IL4R, and decreases in interferon-stimulated genes (IFI44L, STAT1, IFITM1, MX1, IRF1)." (PMID 34583709, 2021). "Although several reports found that IFITM1 promoted tumor metastasis in various cancers including NSCLC, this is the first report to our knowledge demonstrating that IFITM1 plays an important role in SCLC metastasis." (PMID 32668617, 2020). "In many of these cancers, it was demonstrated that IFITM1 is also involved in tumor growth in vitro and/or in vivo." (PMID 32668617, 2020). "After verifying our RNA sequencing results, we determined that AT-MSCs enhanced the efficacy of RT on tumor regression via inhibition of interferon-induced transmembrane 1 (IFITM1) gene expression." (PMID 31781559, 2019). "RNA-sequencing analysis revealed a noticeable interferon-induced transmembrane 1 (IFITM1)-induced tumor gene signature." (PMID 31781559, 2019). "IFITM1 was almost undetectable in samples from normal area, whereas it was highly increased in samples from tumor and metastatic regions." (PMID 27852071, 2016). "We analyzed IFITM1 mRNA level in 23 patient-derived samples obtained from normal area (n = 10), tumor area (n = 10) and metastatic area (n = 3) by RT-qPCR." (PMID 27852071, 2016). "An upregulation of IFITM1 in different types of cancer and promotion of tumorigenesis by enhancing tumor cell migration, invasion and proliferation has been reported in several studies but the opposite has also been shown." (PMID 27186374, 2016). "After investigating the gene expression profiles of 20 KYSE human ESCC cell lines and 18 tumor samples, they demonstrated that interferon induced transmembrane protein 1 (IFITM1) gene was possibly a key determinant of the CDDP sensitivity." (PMID 20514215, 2009). "However, both the tissue specificity of the RRBP1-ALK fusion and the tumor suppressor function of IFITM1 by maintaining it in NFPA caution against a one-size-fits-all solution." (PMID 41200062, 2026). "We demonstrated that PRDM6 expression occurs almost exclusively in tumor cells of clinical HNSCC tissues and that PRDM6 promotes proliferation and growth of HNSCC tumor cells in vitro while suppressing expression of anti-tumor ISGs (ISG15, IFITM1) by both loss- and gain-of-function approaches." (PMID 40936897, 2025). "Furthermore, Dhx9, Dusp12, Fhl1, and Ifitm1 are each correlated with the invasion of tumor‐infiltrating immune cells into the microenvironment." (PMID 38193115, 2024).
tumor (continued). "However, the molecular function of IFN-γ-mediated IFITM1 at the cellular level during tumor progression remains controversial." (PMID 39273214, 2024). "IFITM1 expression in tumor tissues was examined in S100-positive Schwann cells." (PMID 39273214, 2024). "Overexpression of IFITM1 in NF1-associated MPNST cells caused a significant decrease in Ras activation (GTP-Ras) and downstream ERK1/2 phosphorylation, indicating that the expression level of IFITM1 was inversely correlated with tumor progression in NF1." (PMID 39273214, 2024). "IFITM1 was highly expressed and spatially restricted relative to the annotated tumor regions." (PMID 38729966, 2024). "Finally, we demonstrated that interferon-gamma (IFN-γ), which is known to induce IFITM1 expression, suppressed tumor progression in xenograft mice injected with MPNST cells." (PMID 39273214, 2024). "IFITM1 expression was positively related to tumor proliferation, invasion, and metastasis." (PMID 37968723, 2023). "IFITM1 might play an important role in the tumor immune microenvironment of PRAD via the regulation of tumor-infiltrating immune cells." (PMID 36591519, 2022). "With regard to IFITM1, also known as 9-27 or Leu13, is reported to be overexpressed in a wide range of neoplasms and thought as an independent prognostic biomarker for patients with certain tumor types." (PMID 35345444, 2022). "Our findings showed that IFITM1 expression was downregulated in PRAD tumor samples." (PMID 36591519, 2022). "Overall, our findings suggested LINC00847 may exhibit its tumor-pro motive effects on the NSCLC progression by increasing IFITM1 expression via sponging miR-147a." (PMID 33968966, 2021). "Furthermore, these studies demonstrated a positive correlation between IFITM1 overexpression and tumor progression, too." (PMID 32626514, 2020). "Therefore, it is possible that IFITM1 expression in SCLC cells was induced by IFNs in the tumor microenvironment." (PMID 32668617, 2020). "For PC2, top positively correlated genes included IFITM1 and GPX1, both have been reported to be associated with risk of numerous cancers, while most negatively PC2 correlated genes included common-known tumor over-expressed genes such as EFNA1." (PMID 32231683, 2020). "The strong induction of IFITM1 may occur in a small portion of tumor cells in the primary tumor tissues because we detected relatively weak IFITM1 expression in the orthotopic tumors in our model and the primary tumors of patients with SCLC." (PMID 32668617, 2020). "The exact function of IFITM1 in malignancy is poorly understood and its role might differ depending on tumor cell type and context." (PMID 27186374, 2016). "To identify the factors contributing to the aggressive phenotype of IBC cells, we measured the expression of IFITM1, an ISG linked to tumor progression, in three IBC cell lines: triple-negative SUM149, HER2-amplified SUM190 and MDA-IBC-3, and the non-IBC cell line MCF-7 (ER+)." (PMID 26897526, 2016). "Based on our data, the fact that IFITM1 can function as a negative regulator of cell proliferation, and because the gene maps to chromosome band 11p15.5, previously associated with NSCLC, it is likely that IFITM1 in man has a key role in tumor formation." (PMID 23115618, 2012). "Since IFITM1 has been proposed as a negative regulator of cell proliferation, it might have a key role in tumor formation." (PMID 23115618, 2012). "Moreover, the low expression of IFITM1 was also related to worse overall survival in the T stage (p = 0.031), the white subgroup of the race (p = 0.049), N stage (p = 0.035), M stage (p = 0.018), and residual tumor (p = 0.038) (–F)." (PMID 36591519, 2022). "In order to avoid the influence of hormones on tumor expression, combined with clinical information, we divided the patients into two groups of pre- and post-menopausal women, and compared the expression of IFITM1, CD10, h-caldesmon, and SMA in EST and CL between pre- and post-menopausal women." (PMID 34556086, 2021).
tumor (continued). "It has been discovered that IFITM1 could act a tumor suppressor role in HCC." (PMID 31781559, 2019). "The expression analysis showed significant downregulation of IFITM1 in tumor tissue, while IFIT1 was upregulated in both tumor and normal tissue after CRT." (PMID 40646573, 2025). "Second, depletion of endogenous PRDM6 by siRNA knockdown induced the expression of anti-tumor ISGs, ISG15 and IFITM1." (PMID 40936897, 2025). "Compared to other EC subtypes,EC4 exhibited elevated expression levels of multiple genes implicated in antigen presentation (HLADRB1,HLA-DRB5,and HLA-DRA),immune cell recruitment (SELP,LIFR, and ACKR1),and anti-tumor inflammation (CCL14,IFITM1)." (PMID 41394809, 2025). "This assay demonstrated that both IFITM1 KO and IFITM1+3 KO cells are significantly more resistant to NK cell-mediated killing, as evidenced by a lower percentage of dead (7-AAD+) tumor cells after 4 h of co-cultivation." (PMID 40314078, 2025). "Here we demonstrate that high expression of IFITM1 in ASCC was associated with high PD-L1 expression on tumor cells (TPS), and on immune and tumor cells combined (CPS), which is in line with the notion of an immunoregulatory role of IFITM1 in ASCC18,28." (PMID 38653773, 2024). "Therefore, IFITM1 may be a potential biomarker for evaluating tumor progression in NF1." (PMID 39273214, 2024). "In xenograft mice injected with MPNST cells, IFN-γ treatment successfully suppressed tumor progression with increased IFITM1 expression and decreased Ras and ERK1/2 activation in tumor tissues." (PMID 39273214, 2024). "The tumor cells usually exhibit positive immunohistochemical staining for CD10, WT-1, interferon-induced transmembrane protein-1 (IFITM1), ER, and PR." (PMID 39263529, 2024). "IFITM1 gene was particularly overexpressed in the CDH1-TANGO6 deletion, a feature previously observed in several aggressive tumours, and shown to enhance tumour proliferation and invasion." (PMID 37249750, 2023). "Immunohistochemically, the tumor cells showed diffuse positivity for TFE3, CD10, vimentin, and IFITM1." (PMID 36707859, 2023). "IFITM1 and IFITM3 are both overexpressed in most tumor tissues, whereas IFITM2 is overexpressed in only some tumor types and even downregulated in others." (PMID 36466909, 2022). "The IFIT1, ISG15, IFITM1 and IFI27 genes are related to activation of the interferon gamma (IFNγ) response, suggesting possible inflammatory responses in NR tumour samples." (PMID 35053540, 2022). "The authors then focused on IFITM1 and verified this result in vitro and in vivo using oral squamous cell carcinoma cell lines (CAL27 and TSCC-1) and a tumor model established in nude mice." (PMID 36466909, 2022). "The IFITM1 expression was significantly correlated with M stage, N stage, T stage, PSA, Gleason score, primary therapy outcome, residual tumor, DSS event, and OS event." (PMID 36591519, 2022). "Consistent with mouse Kras tumor data, there appeared to be a significant downregulation of anti-tumor immune responses and decrease in IFN signaling genes such as IFITM1 in MGA-altered cases." (PMID 34236315, 2021). "To further study the regulation of IFITM1, we isolated organoids from the normal colon (NCO) and from the tumor (CRCO) of CRC patients." (PMID 34609520, 2021). "Here we found that both IFITM1 and KAL1 expression were higher in DIPG tumor samples than in their paired normal brain tissues, although only KAL1 proved to be statistically significant probably due to the small number of collection." (PMID 32626514, 2020). "We next found that silencing of either IFITM1 or KAL1 by RNAi effectively repressed DIPG cell growth, inducing tumor cell apoptosis in a manner similar to treatment with ABC294640." (PMID 32626514, 2020). "We found that knockdown of either SphK1 or SphK2 effectively reduced IFITM1 and KAL1 expression indicating sphingolipid metabolism indeed regulates these cellular genes expression and functions to determine tumor cell survival." (PMID 32626514, 2020).
tumor (continued). "Several of these genes, including IFI27, IFITM1, IRF1, STAT1, IF16, and TAP1, are known to possess potent anti-proliferative and tumor suppressive properties." (PMID 29176033, 2017). "The differentially enriched regions for active histone marks also included the loci for the neutrophil chemoatractants Cxcl3/5, and the interferon-response induced Ifitm1/2/3, which were higher in the SCC tumours." (PMID 28387316, 2017). "We found that 7 genes (IFITM1, SMAD6, TBX15, CHST4, LRRC4, CCL20, and NQO1) showed significantly different promoter methylation levels between tumor and non-tumor tissue (P value < 0.001) in approximately 80 % of the 78 HCCs." (PMID 26300991, 2015). "Using this approach, 7 genes were identified as undergoing tumor-specific aberrant promoter methylation in HCC, including IFITM1, SMAD6, TBX15, CHST4, and LRRC4 with hyper-methylated promoters and CCL20 and NQO1 with hypo-methylated promoters." (PMID 26300991, 2015). "IFITM1, IFITM2 and IFITM3 have miscellaneous functions including cell adhesion, antiproliferation, tumor suppression and embryonic development." (PMID 23166625, 2012). "IFITM1, IFITM2 and IFITM3 are involved in cell adhesion, antiproliferation, tumor suppression, and germ cell and embryonic development." (PMID 23166625, 2012). "Differential expression analysis of these 27 intersecting genes in the GSE87211 dataset from GEO revealed significant expression differences between tumor and normal groups for 26 genes, with ASCL2, IFITM3, IFITM1, SMPDL3A, and SUCLG2 being the five most significantly differentially expressed." (PMID 41595533, 2026). "Notably, we identified PRDM6, a histone methyl-transferase previously unlinked to HNSCC, as a key regulator of immune gene expression in HNSCC tumor cells, including canonical interferon-stimulated genes (ISGs) such as ISG15 and IFITM1." (PMID 40936897, 2025). "The tumor cells showed diffuse positivity for CD10, IFITM1, CD99 and TFE3 (strong nuclear)." (PMID 36707859, 2023). "KRAS-Mut tumors showed significant upregulation of tumor migration (TGFBR2-S553 and EPHB3) and PI3K/AKT activation (PIP4K2C and PIK3R1), while the KRAS-WT group was enriched in immune regulation (TAP1/2, IFITM1, and IFIH1-S301) and cellular metabolism (DGAT1 and HINT3)." (PMID 35836817, 2022). "Contacts between tumor and NK cells remained unaffected; thus, IFITM1 does not function as an interfering agent." (PMID 36466909, 2022). "IFITM1 expression was significantly correlated ESTIMATE score and tumor purity." (PMID 35619698, 2022). "This review summarizes and discusses current knowledge of IFITM proteins, especially the immune-related proteins IFITM1, IFITM2 and IFITM3, different levels of regulation of their expression and function, and their involvement in immune processes and tumor transformation." (PMID 36466909, 2022). "In contrast to IFITM3, IFITM1 and IFITM2 are less frequently assessed in tumor-focused studies." (PMID 36466909, 2022). "The positive correlation and interaction between IFITM1 and CD81 potentially expands the effect of IFITM1 on antitumor immunity, as CD81 plays an important role in the activities of tumor-infiltrating immunosuppressive cells (MDSCs and regulatory T cells (Tregs))." (PMID 36466909, 2022). "The results showed that in the same tumor, the expressions of IFITM1, CD10, h-caldesmon, and SMA were not statistically different between pre- and post-menopausal groups." (PMID 34556086, 2021). "Overexpression and silencing experiments demonstrated that IFITM1 enhanced metastatic formation without altering the in vivo tumor growth of DMS273 cells." (PMID 32668617, 2020). "We further demonstrated that IFITM1 overexpression did not affect in vivo subcutaneous tumor growth in nude mice." (PMID 32668617, 2020). "The increased expression of IFITM1 may also render SCLC cells resistant to natural killer cells, and the cells may in turn be able to escape from tumor immune surveillance." (PMID 32668617, 2020).
tumor (continued). "By contrast, we observed that IFITM1 promoted tumor metastasis without any apparent effects on tumor growth, migration, and invasion in DMS273 cells under our experimental conditions." (PMID 32668617, 2020). "The strongly induced IFITM1 should amplify the metastatic potential of SCLC cells, possibly by enhancing the adhesion ability of SCLC cells and/or their resistance to natural killer cells, and these tumor cells would ultimately form distant metastases." (PMID 32668617, 2020). "Furthermore, increased expression of a subset of ISGs, including IFITM1, EIF2AK2, STAT1, and IFI27, has been reported in several types of cancers, and these ISGs have been shown to promote tumor growth and resistance to chemotherapy and radiotherapy." (PMID 26897526, 2016). "Using ROC-curves, both for the separate primary tumor locations and for the entire cohort and with regard to TTR as well as OS, an optimal cut-off at 3 (IFITM1 low < 3, IFITM1 high 3–12) was identified and subsequently used for both TTR and OS, irrespectively of tumor location." (PMID 27186374, 2016). "Importantly, we previously reported that MCL1, IFITM1, and USP18 are co-expressed with STAT1 in the IR- and IFN-resistant nu61 tumor." (PMID 19503789, 2009). "However, validation of these findings in tissues from COAD patients using the RT–qPCR showed that IFITM3, but not IFITM1, was highly expressed in the tumor, which indicated the positive association of IFITM3 expression with the disease progression." (PMID 38167862, 2024). "Here, we provide a summary of the current knowledge on the roles of the IFITM1, IFITM2 and IFITM3 proteins in different types of tumors and the molecular mechanism, effect on anticancer therapy and links between IFITM-interacting partners with an overlap with tumor progression." (PMID 36466909, 2022). "Conversely, orthotopic tumor growth was not affected by IFITM1 silencing." (PMID 32668617, 2020). "Whereas IFITM1 expression was only detected in some SCLC cell lines and lung tumors from patients with SCLC, the tumor cells isolated from metastatic sites highly expressed IFITM1 compared with its levels in tumor cells from orthotopic sites in our SCLC metastasis model." (PMID 32668617, 2020). "Thus, IFITM1 overexpression significantly enhanced distant metastatic formation but did not affect the in vivo tumor growth of DMS273-GFP cells." (PMID 32668617, 2020). "Expression of IFITM1 was significantly elevated in primary tumors and lymph node metastases compared to adjacent normal epithelium and intestinal metaplasia, regardless of tumor location." (PMID 27186374, 2016). "Concurrent expression of IFITM1, FOXM1, and PLK1 showed a high correlation with tumor formation in primary and advanced LUAD but not in LUSQ." (PMID 37968723, 2023).